ID4 (inhibitor of DNA binding 4)
Diseases named in the same sentence as ID4 in open-access papers (continued):
Sharing a sentence is not in itself a finding about the gene and the disease.
breast cancer (continued). "To confirm that ID4 behaves as a tumor suppressor only in ER+ breast tumors, we tested the effect of ID4 overexpression in the ER− breast cancer cell line MDA-MB231." (PMID 30139383, 2018). "An increased level of Id4 has been observed in basal-like breast cancer, triple-negative breast cancer, glioblastoma, primary serous ovarian cancer, and melanoma, leading to the qualification of Id4 as a proto-oncogene." (PMID 28143562, 2017). "ID4, upregulated in the offspring of HF diet-fed dams, is associated with poor prognosis of breast cancer, inhibits BRCA1 function in basal-like breast cancer, and promotes chemoresistance." (PMID 28673325, 2017). "More recently Brogie’s group have shown that in a large series of primary breast cancers at the Memorial Sloan Kettering Cancer Center (MSKCC) 40% of 101 TNBCs had high levels of ID4 immunoreactivity compared to only 5% of 113 HR+ve tumors." (PMID 27077368, 2016). "In this regard, studies from breast cancer are particularly interesting that demonstrate both pro- and anti-tumor function of Id4." (PMID 23342267, 2012). "On the other hand ID4 was identified as an upstream regulator of BRCA1 in breast and ovarian cancer, and more aggressive breast cancer types showed higher ID4 expression." (PMID 20070914, 2010). "In parallel to these findings, obtained in cell lines, the staining of 110 breast cancers for the CD31 blood vessels marker revealed higher microvessel density in the Id4-positive population than that in Id4-negative." (PMID 21293053, 2010). "Analysis of the methylation status of Id4 promoter in breast cancer cell lines and tissues has indicated that hypermethylation is a frequent event and is associated with an increased risk of lymph node metastasis." (PMID 21293053, 2010). "Id4 promoter was also found hypermethylated in a variety of other malignancies, such as leukemia, prostate cancer and breast cancer." (PMID 21293053, 2010). "In breast cancer, methylation-related silencing of ID4 is a poor prognostic indicator, and demethylation is proposed as a means of overcoming ID4 repression." (PMID 21194482, 2010). "Among those genes, ID4 was found to be a novel tumor suppressor gene in normal human breast tissues and epigenetically silenced in breast cancer cell lines and primary breast tumors." (PMID 19116033, 2008). "ID4 promoter methylation, ID4 mRNA expression and ID4 protein expression were analysed in primary human breast cancer specimens using methylation-specific PCR (MSP) (n=170), semiquantitative realtime RT-PCR (n=46) and immunhistochemistry (n=3), respectively." (PMID 18513385, 2008).
breast cancer (continued). "In breast cancer the epigenetic regulation of ID4 expression was demonstrated in 67% (16/24) of node positive tumours, although only breast tumours of small size (T1 tumours) were analysed in this study." (PMID 18513385, 2008). "Aside from these expression data, a role of ID4 as a putative tumour suppressor in human breast cancer development has been discussed controversially and is uncertain yet." (PMID 18513385, 2008). "Breast cancer specimens (T) with unmethylated ID4 promoter exhibited only a marginal decline (FC = 1.1) in ID4 mRNA expression." (PMID 18513385, 2008). "Furthermore, we could show that ID4 promoter methylation in human breast cancer is significantly associated with loss of ID4 mRNA expression, this tight correlation again being a prerequisite for a putative tumour suppressive function of ID4 promoter methylation in human breast cancer." (PMID 18513385, 2008). "In conclusion, our data show that ID4 is a potential tumour suppressor gene in breast cancer that becomes epigenetically inactivated during cancer development owing to aberrant promoter methylation." (PMID 18513385, 2008). "The aim of the present study was to reveal the factual role of ID4 in carcinogenesis in more detail, since its role for the pathogenesis of human breast cancer has been discussed controversially, assigning both oncogenic and tumour suppressive functions." (PMID 18513385, 2008). "The loss of protein expression, which modulates the activity of its downstream targets, is an important milestone for the validation of ID4 as a novel TSG in human breast cancer." (PMID 18513385, 2008). "Supporting a metastasis suppressing function of ID4, we found a significant positive correlation between ID4 promoter methylation and lymph node metastasis in our large cohort (n = 170) of breast cancer patients." (PMID 18513385, 2008). "In order to determine the exact methylation frequency of the ID4 promoter in a clinical relevant spectrum of human breast cancer we analysed genomic DNA from 170 primary breast cancer patients by MSP technology." (PMID 18513385, 2008). "In the present study, we readdressed the role of ID4 promoter methylation in human breast cancer development." (PMID 18513385, 2008). "These cell line results represent the prerequisite for a putative tumour suppressive role of ID4 promoter methylation in human breast cancer." (PMID 18513385, 2008). "Our investigations form a basis for further functional analyses in order to light up the importance of ID4 for the progression and metastasis of human breast cancer." (PMID 18513385, 2008). "Breast cancer specimens exhibited strong ID4 mRNA downregulation (16-fold and 71-fold, respectively) in comparison to their corresponding normal tissues depending on clear ID4 promoter methylation." (PMID 18513385, 2008). "Recently we have demonstrated that ID4 mRNA expression is downregulated in 78% (39/50) of human primary breast carcinomas." (PMID 18513385, 2008). "This review summarizes and analyzes the relevant studies of ID4 and the research progress in breast cancer, integrating the development of breast tissue and tumorigenesis with the regulatory role of ID4, to provide some insights into develop new treatment strategies and diagnostic biomarkers." (PMID 40186425, 2025). "However, more research is needed to fully understand the relationship of the Kennedy pathway together with ID4 in breast cancer." (PMID 38332687, 2024). "We next explored whether ID4 expression correlates with YAP/TAZ signaling in human breast cancer patients." (PMID 38321003, 2024). "ID4 is important for both mammary gland development and also for the etiologic of breast cancer." (PMID 38332687, 2024). "Besides this, ID4, SEMA3F, FOXD, KCNK5, WNK4 and ECM1 associate with chemoresistance origin and SOX5, ITM2A, SNCG, EPHA4, NTS, FGFR2 and ENPEP associate moreover with breast cancer tumorigenesis." (PMID 37239828, 2023).
breast cancer (continued). "Additionally, miR-342-3p was found to target the Inhibitor of Differentiation 4 (ID4) and operate as a possible tumor suppressor by preventing the metastasis and chemoresistance of breast cancer cells." (PMID 37397377, 2023). "Whether Slug regulates ID4 as well as its downstream targets and confers drug resistance in breast cancer awaits further investigation." (PMID 36291790, 2022). "Indeed, expression of ID4 was found to be elevated in aggressive breast cancer human tissue mainly the TNBC and HER2 enriched samples as compared to the normal breast epithelium." (PMID 36510219, 2022). "Emerging evidence has shown a proto-oncogenic role of ID4 in basal like breast cancer (BLBC)." (PMID 33593445, 2021). "In conclusion, ID1 and ID4 may act as biomarkers of tumor aggressiveness and worse prognosis in breast cancer, and they could be used as potential targets for new treatments discover." (PMID 33514024, 2021). "This induction is strictly dependent on the ID4 expression levels in breast cancer cells." (PMID 32054109, 2020). "Interestingly, efficient induction of ID4 in macrophages is obtained only if high levels of ID4 are present in breast cancer cells." (PMID 32054109, 2020). "As MyoD1 was reported as a negative regulator in breast cancer, these evidences indicated that ID4 could promoted the expression of CBF1 by weakening the inhibition of MyoD1 on CBF1 transcription in breast cancer." (PMID 32328189, 2020). "In breast cancer, ID4 is considered as the key controller of luminal differentiation pathways, and ID4 expression is almost absent in ERα breast cancer cells, indicating that ERα might negatively regulate ID4 function." (PMID 32328189, 2020). "Moreover, ID4 enhances the angiogenic potential of breast cancer cells through the post-transcriptional regulation of IL8, CXCL1, and VEGFA mRNAs and through the reprogramming of tumor-associated macrophages." (PMID 32054109, 2020). "In addition, knockdown of ID4 in TNBC breast cancer lines significantly suppressed the proliferation, migration, invasion and Adriamycin resistance in vivo or in vitro." (PMID 32328189, 2020). "To shed light on whether ID4 modulates breast cancer cell proliferation in TNBC cell lines, we infected MDB-MA-231 and MCF-7/Adr cell lines with lentiviruses expressing small hairpin RNAs (shRNAs) to knockdown ID4 expression." (PMID 32328189, 2020). "We next analyzed whether the ID4 expression level changes in macrophages cultured in conditioned medium (CM) from breast cancer cells." (PMID 32054109, 2020). "ID4 serves as hypermethylation gene and tumor suppressor gene in breast cancer and acute leukemia." (PMID 31956659, 2019). "To evaluate whether the expression level of ID4 could have any predictive value for breast cancer overall survival (OS), we used the online survival analysis software, Kaplan–Meier (KM) plotter." (PMID 30139383, 2018). "Therefore, enough evidence exists to conclude that ID4 can assume distinct roles in breast cancer, depending on the cellular context." (PMID 30139383, 2018). "The reduction in migration could be related to the fact that we found ID4 associated with CCND1, which regulates migration and proliferation in breast cancer cells; perhaps, these changes in migration are due to an interaction between ID4 and CCND1." (PMID 30139383, 2018). "We hypothesize that ID4 acts as both, tumor suppressor and oncogene, but its role will differ according to the ER status of the breast cancer cell." (PMID 30139383, 2018). "Ours is the first report suggesting an association between ID4 and CCND1 in breast cancer." (PMID 30139383, 2018). "Finally, the putative tumor suppressor function of ID4 in ER+ breast cancer was verified by in vitro assays." (PMID 30139383, 2018). "We also evaluated the effect of ID4 expression on OS in breast cancer patients." (PMID 30139383, 2018).
breast cancer (continued). "By culturing macrophages in conditioned media obtained from breast cancer cells in which ID4 expression was modulated by overexpression or depletion, we identified changes in the expression of ID4-dependent angiogenesis-related transcripts and microRNAs (miRNAs, miRs) in macrophages by RT-qPCR." (PMID 29921315, 2018). "In breast cancer, our group and others have previously shown that ID4 may behave as an oncogene in TNBC or basal-like breast tumors." (PMID 30139383, 2018). "Our present study contributes to the knowledge of the role of ID4 in breast cancer." (PMID 30139383, 2018). "In various human tumor types such as acute and chronic leukemia, different malignant lymphomas, colorectal carcinoma, breast cancer and gastric carcinoma, the tumor suppressor activity of Id4 is abrogated through epigenetic inactivation of its promoter by methylation during cancer development." (PMID 28122577, 2017). "ID4 is expressed in breast cancer and can negatively regulate BRCA1 expression." (PMID 24475217, 2014). "Based on these findings, we hypothesized that regulation of ID4 mediated by miR-342 could be involved in the pathogenesis of breast cancer by downregulating BRCA1 expression." (PMID 24475217, 2014). "ID4 is most recently discovered member of ID genes, mainly express in thyroid and several other tissues, and a previous study has already reported it as a marker in breast cancer." (PMID 24718460, 2014). "ID4 belongs to a family of dominant negative regulators of basic helix-loop-helix transcription factors and is highly expressed in diverse cancer types, including breast cancer." (PMID 24475217, 2014). "To investigate at functional level the role of miR-342 in the pathogenesis of breast cancer, we focused our attention on its “in silico” predicted putative target gene ID4, a transcription factor of the helix-loop-helix protein family whose expression is inversely correlated with that of ER." (PMID 24475217, 2014). "But studies have also demonstrated epigenetic silencing of Id4 in breast cancer." (PMID 23342267, 2012). "We found that Id4 is expressed in 44% of the breast cancer specimens analyzed (186 patients)." (PMID 21293053, 2010). "In other studies, Id4 was down regulated due to promoter hypermethylation in breast cancer." (PMID 19500415, 2009). "The methylation status of ID4 predicts early tumour relapse and could serve as a prognostic biomarker in human breast cancer." (PMID 18513385, 2008). "Using in vitro DNA demethylation treatment of human breast cancer cell lines we wanted to determine whether ID4 promoter hypermethylation may affect ID4 mRNA transcription." (PMID 18513385, 2008). "Thus, it was the aim of the present work to analyse the role of ID4 promoter methylation in a clinical relevant cohort of human breast cancer and further to study this process in human cell lines." (PMID 18513385, 2008). "In total ID4 promoter methylation was found in 68.9% (117/170) of breast cancer specimens." (PMID 18513385, 2008). "ID4 in particular has been shown to be overexpressed in rat mammary carcinomas." (PMID 15876350, 2005). "However, the role of the remaining ID family members, especially ID4, in breast cancer remains unclear." (PMID 33514024, 2021).
breast cancer (continued). "Interestingly, co-culture of macrophages with breast cancer cells whose ID4 expression has been inhibited by siRNA transfection (si-ID4#1, si-ID4#2) led to a significantly attenuated ID4 induction in macrophages, compared to co-culture with control cells (si-SCR)." (PMID 32054109, 2020). "In addition, we also tested ID4 expression in breast cancer cell lines." (PMID 32328189, 2020). "Moreover, as we previously observed that the ID4 protein controls VEGFA expression in breast cancer cells, and VEGFA in turn participates in the reprogramming of macrophages in a pro-angiogenic sense, we decided to investigate the impact of VEGFA on ID4 and ARNT expression in macrophages." (PMID 32054109, 2020). "However, it is still unknown whether ID4 can mediate tumor cell sensitivity to chemotherapeutic drugs in breast carcinoma, especially TNBC." (PMID 32328189, 2020). "Functionally, it has been shown that ID4 may exert similar inhibitory effects on BRCA1 and estrogen receptor alpha (ERα) gene expression, and, conversely, BRCA1 and ERα may demonstrate redundancy in inhibiting ID4 gene expression in breast cancer cells and tissues." (PMID 32054109, 2020). "This miRNA could therefore be involved in the modulation of ID4 in breast cancer." (PMID 24475217, 2014). "However, another study suggested that ID4 may act as tumour suppressor gene in a fraction of primary breast cancers, since aberrant hypermethylation of the ID4 gene promoter in T1 tumours was associated with an increased risk for lymph node metastasis." (PMID 18513385, 2008). "In addition, we could show that a high percentage of human primary breast cancers (69%) exhibit hypermethylation of the ID4 promoter." (PMID 18513385, 2008). "Therefore, ID4 expression might discriminate LumA breast cancers with more aggressive phenotypes." (PMID 38321003, 2024). "In this study, we investigated the role of ID4 in the metastasis of TNBCs within the framework of the ELK3 axis, which acts as a master regulator of EMT in various malignancies, including breast cancer." (PMID 38188675, 2023). "Down-regulation of ID4 in MCF-7/Adr and MDA-MB-231 breast cancer cell lines significantly suppressed cell proliferation and invasion, however enhanced Adriamycin sensitivity." (PMID 32328189, 2020). "However, it is unknown whether ID4 affected Notch signaling in breast cancer." (PMID 32328189, 2020). "In breast cancer, CD109, ID4, and ST8SIA1 are involved in the maintenance of stem cell phenotype, whereas NR4A1 promotes TGF-β-induced EMT and invasion." (PMID 32679794, 2020). "The expression of ID4 in MCF-7, MCF-7/Adr and MDA-MB-231 breast cancer cell lines and patients' tissues were detected by RT-PCR, western blot and immunohistochemistry." (PMID 32328189, 2020). "We reveal for the first time that ID4 performs its function via a CBF1-MRP1 signaling axis, and this finding provides a novel perspective to find potential therapeutic targets for breast cancer chemotherapy." (PMID 32328189, 2020). "A positive correlation between the expression of ID4 and C-promoter binding factor-1(CBF1, a critical downstream transcriptional factor in Notch1 signal pathway) was observed in both TNBC breast cancer cell lines." (PMID 32328189, 2020). "Interestingly, eight genes (ID4, LTBP4, GPM6B, RGMA, EFCAB1, ALX4, OSR1 and PPARA) were confirmed to be down-expressed in breast cancer tissues, and associated with the overall survival time of breast cancer patients, as high expression of these genes correlate with an improved prognosis." (PMID 32650755, 2020). "In the context of BC, ID4 is highly expressed in triple-negative breast cancer (TNBC), 70% of which belong to the basal-like breast cancer (BLBC) molecular subtype." (PMID 29921315, 2018). "In vitro experiments involved ectopic expression of ID4 in MCF-7, T47D, and MDA-MB231 breast cancer cell lines." (PMID 30139383, 2018).